KCNMB3 (potassium calcium-activated channel subfamily M regulatory beta subunit 3)
Description:
Regulatory subunit of the calcium activated potassium KCNMA1 (maxiK) channel. Modulates the calcium sensitivity and gating kinetics of KCNMA1, thereby contributing to KCNMA1 channel diversity. Alters the functional properties of the current expressed by the KCNMA1 channel. Isoform 2, isoform 3 and isoform 4 partially inactivate the current of KCNBMA. Isoform 4 induces a fast and incomplete inactivation of KCNMA1 channel that is detectable only at large depolarizations. In contrast, isoform 1 does not induce detectable inactivation of KCNMA1. Two or more subunits of KCNMB3 are required to block the KCNMA1 tetramer.
Synonyms: BKbeta3; Hbeta3; KCNMB2; KCNMBL; K(VCA)BETA-3; SLO-BETA-3; SLOBETA3
Tractability: Antibody: its Gene Ontology location is reachable by antibodies, with high confidence; UniProt predicts a signal peptide or a membrane-spanning region.
Gene: Protein-coding gene on chromosome 3 (179,236,691 to 179,267,002, reverse strand). Ensembl gene ENSG00000171121.
Subcellular location: Membrane
Subcellular location (Human Protein Atlas): Nucleoplasm; Mitochondria
Pathways (Reactome):
Hemostasis: cGMP effects
Neuronal System: Ca2+ activated K+ channels
Gene Ontology:
Molecular function: calcium-activated potassium channel activity; potassium channel regulator activity
Biological process: action potential; detection of calcium ion; neuronal action potential; potassium ion transport; potassium ion transmembrane transport
Cellular component: plasma membrane; voltage-gated potassium channel complex; membrane
Genetic constraint (gnomAD): Loss-of-function variants: 17 observed, 11.31 expected, observed/expected ratio (o/e) 1.5, 90% interval 1.01 to 1.92. The synonymous counts are far from expectation, so gnomAD's model fits this gene poorly and the ratio says little. Missense variants: 205 observed, 247.99 expected, observed/expected ratio (o/e) 0.83, 90% interval 0.74 to 0.93. Synonymous variants: 63 observed, 89.46 expected, observed/expected ratio (o/e) 0.7, 90% interval 0.57 to 0.87.
Homologues: Orthologues: chimpanzee KCNMB3 (92% identical), macaque KCNMB3 (88% identical), pig KCNMB3 (76% identical), dog KCNMB3 (76% identical), rabbit KCNMB3 (75% identical), guinea pig KCNMB3 (74% identical), rat Kcnmb3 (59% identical), mouse Kcnmb3 (57% identical), tropical clawed frog kcnmb3 (57% identical), zebrafish kcnmb3 (29% identical). Paralogues in human: KCNMB2 (33% identical), KCNMB4 (23% identical), KCNMB1 (22% identical).
Diseases named in the same sentence as KCNMB3 in open-access papers:
KCNMB3 is named in the same sentence as 6 diseases in open-access papers, as found by Europe PMC text mining. Sharing a sentence is not in itself a finding about the gene and the disease. The quoted sentences say what the papers report.
epilepsy (1 paper, 2012). A brain disorder characterized by episodes of abnormally increased neuronal discharge resulting in transient episodes of sensory or motor neurological dysfunction, or psychic dysfunction. "In patients with epilepsy, an association with a truncation mutation of the KCNMB3 gene has been described which is partly affected from the duplication on chromosome 3." (PMID 22830313, 2012).
generalized epilepsy (1 paper, 2025). Epilepsy that is characterized by generalized seizure types and may have typical interictal and/or ictal EEG findings that accompany generalized seizure types (for example generalized spike-wave). "Alteration in the regulatory β3-subunit as a result of a single base pair deletion in the KCNMB3 gene is associated with generalized epilepsy." (PMID 41465576, 2025).
KCNMB3 also shares sentences with these, for which no sentence is quoted: cancer (1 paper); glioma (1); Insulin resistance (1); lung carcinoma (1).